ZAP70 (zeta chain of T cell receptor associated protein kinase 70)
Diseases named in the same sentence as ZAP70 in open-access papers (continued):
Sharing a sentence is not in itself a finding about the gene and the disease.
lupus (5 papers, 2014 to 2023). "Reduction of Lck, Lat, Zap70 and Prdm1 expression in T cells and a SNP mutation in Ptpn22 have been associated with rheumatoid arthritis, systemic lupus erythematosus and T1D in humans." (PMID 31235823, 2019). "Dephosphorylated Elf-1 fails to associate with the DNA and initiate transcription of CD3ζ transcription, leading to the increased FcRγ and CD3ζ ratio, favouring subsequent activation of the Syk instead of ZAP-70 pathways in lupus T cells." (PMID 24864268, 2014). "Thus, in lupus T-cells, the FcRγ chain binds with another type of tyrosine kinase Syk instead of ZAP-70." (PMID 37215992, 2023). "This is also the case for prolidase D (PEPD) deficiency, which has been associated with the development of systemic lupus erythematosus (SLE), and zeta chain of T cell receptor-associated protein kinase 70 (ZAP-70) and nuclear factor of activated T cells 5 (NFAT5) deficiencies." (PMID 31849949, 2019). "Instead of coupling with ZAP-70 for signalling by the CD3ζ subunits, FcRγ associates with the Syk pathway and such “rewired” downstream signalling confers stronger phosphorylation of signalling molecules and higher calcium influx which intensifies the TCR-derived signals in lupus T cells." (PMID 24864268, 2014).
Lymphadenopathy (4 papers, 2016 to 2021). Enlargement (swelling) of a lymph node. "These are assisted by several clonal factors that potentiate migratory responses favoring clinical lymphadenopathy and poor outcome, including the presence of certain adverse prognostic factors such as CD38, ZAP70, CD49d, trisomy 12, NOTCH1 mutations, or un-mutated IGHV." (PMID 33841445, 2021). "Accordingly, patients with trisomy 12 or ZAP-70 expression may show exacerbated lymphadenopathy but the molecular mechanisms underlying this clinical association have been largely unknown until recent works by Legler ́s laboratory." (PMID 33841445, 2021).
lymphopenia (4 papers, 2019 to 2025). Reduction in the number of lymphocytes. "Immunological workup at 18 years of age showed CD4+ and CD8+ T-cell lymphopenia, and genetic analysis revealed a homozygous pathogenic ZAP70 splice-site mutation (c.402 + 2 T>C)." (PMID 40901120, 2025). "Genetic analyses were performed on four patients with CD8 lymphopenia and a high resolution melting screening for ZAP70 mutations was developed." (PMID 37313400, 2023). "This case underscores the importance of considering ZAP70 mutations in patients with unexplained lymphopenia and recurrent infections even in the absence of classical SCID features." (PMID 40901120, 2025). "Immunologically, all but ZAP70 present with early onset progressive CD4 lymphopenia." (PMID 38112969, 2023). "Isolated CD8 lymphopenia with preserved CD4 counts can be seen with TAP1, TAP2, and ZAP70 defects." (PMID 31572360, 2019).
melanoma (4 papers, 2014 to 2024). A malignant, usually aggressive tumor composed of atypical, neoplastic melanocytes. "Indeed, enhanced phosphorylation of ZAP-70 was observed when TIL14 cells were incubated with control melanoma cells, as compared to basal levels." (PMID 26338962, 2015). "Cognate pMHC on the GUV surface was required to recruit ZAP70 to the membrane, as indicated by the observation that pMHC comprised of a peptide not recognised by the 1G4 TCR (derived from the melanoma antigen gp100) produced no increase in mNeonGreen–ZAP70 fluorescence." (PMID 30209137, 2018).
T cell deficiency (4 papers, 2015 to 2022). "It is worth noting that ZAP70 deletion can cause T cell deficiency diseases with CD8+ T cell selective deletion." (PMID 34869316, 2021). "Dysfunction of ZAP–70 causes selective T cell deficiency that in turn results in persistent infections." (PMID 26473606, 2015).
acute lymphoblastic leukemia (3 papers, 2012 to 2020). Leukemia with an acute onset, characterized by the presence of lymphoblasts in the bone marrow and the peripheral blood. "Subsequent studies further revealed the expression of ZAP-70 in other B cell malignancies, such as Acute Lymphoblastic Leukemia (ALL), Burkitt-lymphoma and Mantle Cell Lymphoma (MCL)." (PMID 33194762, 2020).
atherosclerosis (3 papers, 2023 to 2025). A disease characterized by the build-up of fatty material and calcium deposition in the arterial wall resulting in partial or complete occlusion of the arterial lumen. "ZAP70/NF-κB inhibitors may be a potential therapeutic target for the treatment of P. gingivalis-mediated Th1 cell-related diseases, such as EAE, angiotensin II-dependent hypertension, and atherosclerosis." (PMID 40170858, 2025).
bladder cancer (3 papers, 2020 to 2025). "Moreover, FN1, CXCL12, CD3E, LCK, and ZAP70 were key interconnected node genes in PPI networks and are also associated with overall survival in patients with bladder cancer." (PMID 33204728, 2020).
head and neck squamous cell carcinoma (3 papers, 2019 to 2024). A squamous cell carcinoma that arises from any of the following anatomic sites: lip and oral cavity, nasal cavity, paranasal sinuses, pharynx, larynx, and salivary glands. "The immune-related gene ZAP70 was associated with an increased risk of developing virally mediated head and neck squamous cell carcinoma." (PMID 32286381, 2020).
psoriasis (3 papers, 2016 to 2025). An autoimmune condition characterized by red, well-delineated plaques with silvery scales that are usually on the extensor surfaces and scalp. "The review of SNPs of CSTA, ERAP1 and ZAP70 genes, which were tested for correlation with the risk of psoriasis." (PMID 27658291, 2016). "Case with psoriasis has homozygous DCLRE1C, heterozygous ZAP70, RFX5, AKT1, and NOD2 gene variants, and all of them were VUS variants." (PMID 39992598, 2025). "Similarly, inhibiting the protein product of ZAP70, which is also essential for T-cell signaling, has been shown to have anti-inflammatory properties in vitro and to be effective in treating psoriasis in mice." (PMID 41238958, 2025). "Our aim was to compare psoriasis genetic risk score (GRS) for five susceptibility loci involved in the immunological response (HLA-C, ERAP1, ZAP70) and in the skin barrier function (LCE3, CSTA) between patients with chronic plaque psoriasis (n = 148) and the control group (n = 146)." (PMID 27658291, 2016).
rheumatoid arthritis (3 papers, 2016 to 2022). A chronic, systemic autoimmune disorder characterized by inflammation in the synovial membranes and articular surfaces. "The SKG mouse expresses a hypomorphic mutant allele of ZAP70, which, upon exposure to fungal Ags, predisposes the mice to a CD4+ T cell–mediated autoimmune arthritis that closely resembles rheumatoid arthritis in humans." (PMID 27288531, 2016).
viral infection (3 papers, 2011 to 2023). "Correspondingly, a previous report of a viral infection-specific T-cell immune response induced by a DNA vaccine to the spring viremia of carp virus was identified through the proliferation of Zap70+ T-cells." (PMID 30941134, 2019). "Lack of ZAP–70 expression could be explained by a strong correlation with a basic unmutated IgVH status, not related to the viral infection." (PMID 22567048, 2011).
anaplastic large cell lymphoma (2 papers, 2006 to 2013). Anaplastic large cell lymphoma (ALCL) is a rare and aggressive peripheral T-cell non-Hodgkin lymphoma, belonging to the group of CD30-positive lymphoproliferative disorders, which affects lymph nodes and extranodal sites. "On the one hand, miR-29a and miR-29b are downregulated in mantle cell lymphoma, aggressive CLL samples (high ZAP-70 with unmutated IgVH), ALK-positive anaplastic large cell lymphomas (ALCL), MM, and AML." (PMID 23431463, 2013).
anemia (2 papers, 2016 to 2025). A reduction in the number of red blood cells, the amount of hemoglobin, and/or the volume of packed red blood cells. "High levels of ZAP70 and CD38 are associated with reduced survival in CLL patients, especially in those with unmutated IGHV, and CD38 positivity is frequently found in combination with anemia, thrombocytopenia, and leukocytosis." (PMID 40406271, 2025).
asthma (2 papers, 2021). "With gene‐set enrichment analysis using MAGMA software (in FUMA), we found nine pathways significantly enriched in the GWAS results for FI after adjustment for multiple testing (Bonferroni), including: MHC Class II complex; Translocation of Zap70 to immunological synapse, and asthma (p < 3*10−6)." (PMID 34431594, 2021).
autoimmune lymphoproliferative syndrome (2 papers, 2016 to 2023). Autoimmune lymphoproliferative syndrome (ALPS) is a rare, inherited disorder characterized by non-malignant lymphoproliferation, multilineage cytopenias, and a lifelong increased risk of Hodgkin's and non-Hodgkin's lymphoma. "Moreover, ZAP70 deficiency, autoimmune lymphoproliferative syndrome (ALPS), selective IgA deficiency, and adenosine deaminase (ADA) deficiency have also appeared in differential diagnosis of eosinophilia." (PMID 27222657, 2016).
B cell lymphoma (2 papers, 2016 to 2022). "Our finding of differential ZAP-70 expression between T/NK and B cell lymphoma cell lines is consistent with our current understanding of the biology of B and T-cell signalling." (PMID 35077445, 2022). "Similarities were also noted between CLBL-1 and other targeted B-cell lymphoma gene expression studies, including KIT (almost 400-fold based on qRT-PCR) and ZAP70 downregulation (decreased 10 fold)." (PMID 27639374, 2016). "ZAP-70 protein was highly expressed in T cell lymphoma cell lines (JURKAT and KARPAS-299) and NKTCL cell lines (KHYG-1, HANK-1, NK-YS, SNK-1 and SNK-6), but not in multiple B-cell lymphoma cell lines." (PMID 35077445, 2022).
central nervous system lymphoma (2 papers, 2022 to 2025). "We describe the first reported case of EBV-associated primary CNS lymphoma (PCNSL) in a patient with a novel ZAP70 mutation." (PMID 40901120, 2025). "Given the rarity of CNS lymphomas in ZAP70-deficient patients, further studies and case reports are needed to elucidate the association with CNS tumors, clarify underlying genetic and immunologic risk factors, and guide the development of targeted therapies." (PMID 40901120, 2025).
cervical cancer (2 papers, 2020 to 2023). A primary or metastatic malignant neoplasm involving the cervix. "We identified 79 prognostic TIME-related genes in cervical cancer and validated 4 genes (CCR7, CD28, PD-1, and ZAP70)." (PMID 32733542, 2020).
cervical squamous cell carcinoma (2 papers, 2019 to 2025). A squamous cell carcinoma arising from the cervical epithelium. "In addition, ZAP70 was found to be a prognostic marker for prostate adenocarcinoma and colon cancer response to radiation, as well as cervical squamous cell carcinoma." (PMID 40005847, 2025).
colitis (2 papers, 2008 to 2023). Inflammation of the colon. "Thus, TNBS colitis was characterized by an absence of significant changes in markers of T cells (Thy1, Tcrb, Tcrg, Zap70, Lck), B cells (Ptprc -B220-, Ms4a1 -Cd20-, Cd22, Cd79b) and NK cells (Baat, Ncam1 -Cd56-, B3gat1 -Cd57-)." (PMID 18928539, 2008).
Dry skin (2 papers, 2016 to 2018). Skin characterized by the lack of natural or normal moisture. "In conclusion, our study demonstrates that increased ZAP70 participates in the development of dry skin in elder pruritus via secretion of IL-2 and NGF." (PMID 27195291, 2016). "Another study showed that increased ZAP70 is involved in dry skin in elderly pruritus, while increased secretion of IL-2 and NGF may induce dry-skin itching." (PMID 30018382, 2018). "Our results indicate that increased ZAP70 is involved in dry skin in elderly pruritus." (PMID 27195291, 2016).
Hemophagocytic Lymphohistiocytosis (2 papers, 2021 to 2023). "Patients with ZAP-70 deficiency often present a history of recurrent opportunistic infections, with autoimmunity, or immune dysregulation such as ulcerative colitis and cytopenia, pustular skin lesions, subcutaneous nodules, lymphoma, Omenn syndrome, and hemophagocytic lymphohistiocytosis (HLH)." (PMID 37101133, 2023). "Besides, pustular skin lesions, subcutaneous nodules, Omenn syndrome, and hemophagocytic lymphohistiocytosis (HLH) have been reported in other ZAP-70 deficiency patients." (PMID 37101133, 2023).
laryngeal carcinoma (2 papers, 2022 to 2025). Carcinoma that arises from the laryngeal epithelium. "Expression of AQP9 and ZAP70 was validated in laryngeal cancer tissues and cells by RT-qPCR and immunohistochemistry." (PMID 35477402, 2022). "By RT-qPCR, we detected AQP9 and ZAP70 expression in 30 pairs of laryngeal cancer and adjacent control tissues." (PMID 35477402, 2022). "By univariate cox regression analysis, correction of clinical factors and multivariate cox regression analysis, two IRGs AQP9 and ZAP70 were significantly correlated to survival outcomes of laryngeal cancer." (PMID 35477402, 2022). "To investigate biological functions of AQP9 and ZAP70 during laryngeal cancer progression, we separately silenced and overexpressed AQP9 and ZAP70 in TU212 and LCC cells." (PMID 35477402, 2022). "AQP9 and ZAP70 up-regulation distinctly suppressed proliferation, migration, and invasion of laryngeal cancer cells." (PMID 35477402, 2022). "Transwell assays were applied for evaluating the roles of AQP9 and ZAP70 on migration and invasion of laryngeal cancer cells." (PMID 35477402, 2022). "Firstly, although our data demonstrated the roles of AQP9 and ZAP70 on proliferation, migration and invasion of laryngeal cancer cells, exact molecular mechanisms deserve in-depth observation." (PMID 35477402, 2022). "Our data showed that up-regulation of AQP9 and ZAP70 suppressed proliferation, migration and invasion of laryngeal cancer cells." (PMID 35477402, 2022). "Prognosis-related IRGs were then explored by univariate cox regression analysis and correction of clinical factors, AQP9, CXCL11, IGHV4.31, PDGFA and ZAP70 were significantly correlated to laryngeal cancer prognosis." (PMID 35477402, 2022). "RT-qPCR results demonstrated that AQP9 and ZAP70 mRNA expression was distinctly decreased by their siRNAs and was overexpressed by their overexpression plasmids in laryngeal cancer cells." (PMID 35477402, 2022). "Consistently, ZAP70 was in relation to laryngeal cancer prognosis." (PMID 35477402, 2022). "Combining previous research, AQP9 and ZAP70 mediated laryngeal cancer progression." (PMID 35477402, 2022). "Our findings revealed the roles of AQP9 and ZAP70 in progression of laryngeal cancer, and suggested that AQP9 and ZAP70 could potentially act as candidate immunotherapeutic targets for laryngeal cancer." (PMID 35477402, 2022). "Our findings demonstrated that AQP9 and ZAP70 might be candidate therapeutic targets and prognostic signatures for laryngeal cancer, which may assist guide clinical therapy in the future." (PMID 35477402, 2022). "Low expression of AQP9 and ZAP70 was confirmed in laryngeal cancer." (PMID 35477402, 2022). "Two molecular subtypes based on AQP9 and ZAP70 may reflect immune microenvironment of laryngeal cancer." (PMID 35477402, 2022). "Furthermore, high expression of AQP9 and ZAP70 was significantly correlated to favorable survival outcomes compared to their low expression in laryngeal cancer." (PMID 35477402, 2022). "This indicated that subtypes based on AQP9 and ZAP70 may reflect immune microenvironment of laryngeal cancer." (PMID 35477402, 2022). "Therefore, AQP9 and ZAP70 were identified as prognostic IRGs of laryngeal cancer." (PMID 35477402, 2022). "Hence, AQP9 and ZAP70 might become candidate therapeutic targets and robust prognostic signatures for laryngeal cancer." (PMID 35477402, 2022). "By unsupervised cluster analysis, we constructed two molecular subtypes of laryngeal cancer using ConsensusClusterPlus package based on AQP9 and ZAP70 expression profiles." (PMID 35477402, 2022).
lung carcinoma (2 papers, 2014 to 2022). "As gefitinib is already in clinical use in lung cancer patients, and lacks suppression of the bone marrow or immune system, further studies are warranted to investigate the clinical activity of gefitinib in ZAP-70+ CLL patients." (PMID 25275600, 2014). "In this study the tyrosine kinase inhibitor gefitinib, originally used to inhibit EGFR kinase activation in lung cancer, is also cytotoxic to primary CLL cells that overexpress ZAP-70." (PMID 25275600, 2014). "Thus, although gefitinib is used to treat lung cancer by inhibiting EGFR, it has potential utility in the treatment of CLL patients with high expression of Syk family members that include ZAP-70." (PMID 25275600, 2014).
lymph node metastasis (2 papers, 2018 to 2021). "In addition, the expression levels of COL3A1, COMP, and ZAP70 were positively related to the risk of lymph node metastasis." (PMID 29967488, 2018). "We also found that ZAP70 was positively correlated with lymph node metastasis, so it may be related to the invasion and metastasis of PTC." (PMID 29967488, 2018).
Lymphoproliferative Disorder (2 papers, 2021 to 2025). "Similar cases have been documented in hypomorphic ZAP70 mutations, in which relatively low or fluctuating EBV viral loads are sufficient to precipitate lymphoproliferative disorders due to underlying qualitative immune defects." (PMID 40901120, 2025).
MHC class II deficiency (2 papers, 2019 to 2020). Immunodeficiency by defective expression of HLA class 2 is a rare primary genetic immunodeficiency disorder characterized by partial or complete absence of human leukocyte antigen class 2 expression resulting in severe defect in both cellular and humoral immune response to antigens. "Both TREC copies and ALC/μL are higher in MHC class II deficiency and ZAP70 deficiency than typical SCIDs." (PMID 30778343, 2019).
myeloid leukemia (2 papers, 2024). A clonal proliferation of myeloid cells and their precursors in the bone marrow, peripheral blood, and spleen. "We find that CAR T cells exposed to myeloid leukemia show impaired activation and cytolytic function, accompanied by impaired antigen receptor downstream calcium, ZAP70, ERK, and C-JUN signaling, compared to those exposed to B-cell leukemia." (PMID 39039086, 2024).
Neonatal sepsis (2 papers, 2018 to 2020). Systemic inflammatory response to infection in newborn babies. "These declared that TSPO, MAPK14, and ZAP70 might play critical roles in neonatal sepsis." (PMID 30497506, 2018). "TSPO, ZAP70, CEBPB targeting MAPK14, has-miR-150 targeting BCL11B might affect the pathogenesis of neonatal sepsis." (PMID 30497506, 2018). "Besides, TSPO, ZAP70, CEBPB targeting MAPK14, has-miR-150 targeting BCL11B might act in the pathogenesis of neonatal sepsis." (PMID 30497506, 2018).
non-Hodgkin lymphoma (2 papers, 2021). Distinct from Hodgkin lymphoma both morphologically and biologically, non-Hodgkin lymphoma (NHL) is characterized by the absence of Reed-Sternberg cells, can occur at any age, and usually presents as a localized or generalized lymphadenopathy associated with fever and weight loss. "The screening of ZAP70 also drew our attention, as it was recently found to be a regulatory point of non-Hodgkin lymphoma that acts via the Ras-Raf-dependent pathway and to induce cell apoptosis." (PMID 34966737, 2021).
Omenn syndrome (2 papers, 2023). An inflammatory condition characterized by erythroderma, desquamation, alopecia, chronic diarrhea, failure to thrive, lymphadenopathy, and hepatosplenomegaly, associated with severe combined immunodeficiency (SCID). "Multiple genes presenting as Omenn syndrome, such as RAG1/2, ADA, LIG4, ZAP70, etc." (PMID 37755421, 2023).
peripheral T cell lymphoma (2 papers, 2006 to 2022). "High ZAP-70 expression has been detected by immunohistochemistry in peripheral T cell lymphoma (PTCL) and NK cell lymphomas (NKTCL)." (PMID 35077445, 2022).
Pruritus (2 papers, 2016 to 2018). Pruritus is an itch or a sensation that makes a person want to scratch. "Based on these discussions, the increased ZAP70 cause IL-2 increased and severe pruritus." (PMID 27195291, 2016).